CREB1 (cAMP responsive element binding protein 1)
Diseases named in the same sentence as CREB1 in open-access papers (continued):
Sharing a sentence is not in itself a finding about the gene and the disease.
acute myeloid leukemia (32 papers, 2009 to 2026). Acute myeloid leukemia (AML) is a group of neoplasms arising from precursor cells committed to the myeloid cell-line differentiation. "Increased expression of CREB1 has been reported in acute lymphoblastic leukemia, acute myeloid leukemia, melanoma, hepatocellular, renal cell, ovarian, prostate, lung, and breast carcinoma, brain tumors, etc. compared to their counterpart healthy tissues." (PMID 34641874, 2021). "Additional regulators include aryl hydrocarbon receptor nuclear translocator in acute myeloid leukemia (AML), CREB-1, activating transcription factor 1 (ATF-1), and HIF-1α." (PMID 40722952, 2025). "In acute myeloid leukemia (AML), CREB1 plays a critical role in boosting cell proliferation by regulating RFC3 expression and then promoting the G1/S progression." (PMID 27801665, 2016). "For example, CCNA1 is a target of CREB1 and is upregulated in acute myeloid leukemia while BCL2 is not." (PMID 34641874, 2021).
cardiac hypertrophy (31 papers, 2016 to 2025). "Our data supported a strong association between the activation of CREB1 signaling and the pressure overload-induced cardiac hypertrophy in the WT mice." (PMID 33093614, 2020). "Among these, the involvement of cAMP response element binding protein 1 (CREB1) transcription factor signalling as an important regulator in cardiac hypertrophy has been well acknowledged." (PMID 26930585, 2016). "In the contrast, activated CREB1 may reduce the excessive burden on the heart and heart hypertrophy." (PMID 36304554, 2022). "Additionally, after 8 weeks of TAC, Maresin1 alleviated PO‐induced cardiac hypertrophy and fibrosis, and promoted the deubiquitination and stabilization of PPARα through the PKG/CREB1/USP4 pathway." (PMID 40211903, 2025).
Hyperglycemia (30 papers, 2010 to 2025). An increased concentration of glucose in the blood. "The metabolic disturbances and hyperglycemia in diabetic ischemic heart disease might alter the activity of kinases and transcription factors like DNA-PK, CDC2, MYC, SP1, and CREB1, exacerbating cardiac dysfunction." (PMID 39420368, 2024).
lung adenocarcinoma (28 papers, 2010 to 2025). A carcinoma that arises from the lung and is characterized by the presence of malignant glandular epithelial cells. "The data presented here define that CCDC6, a partner of RET in papillary thyroid carcinoma and in lung adenocarcinoma, fine modulates the CREB1-dependent transcriptional activity through sumoylation both in vitro and in vivo." (PMID 23145146, 2012). "CREB1 has been confirmed as the important therapeutic target in lung adenocarcinoma." (PMID 34513699, 2021). "Additionally, CREB1 upregulates SLC7A11 expression in lung adenocarcinoma." (PMID 41228362, 2025). "In addition to OV, the high alteration frequency of the CREB1 gene was also found in pancreatic adenocarcinoma (PAAD), esophageal carcinoma (ESCA), lung adenocarcinoma (LUAD), lung squamous cell carcinoma (LUSC), and breast invasive carcinoma (BRCA)." (PMID 33921660, 2021).
atherosclerosis (26 papers, 2010 to 2025). A disease characterized by the build-up of fatty material and calcium deposition in the arterial wall resulting in partial or complete occlusion of the arterial lumen. "CREB1 is involved in the regulation of apoptosis, and its overexpression is associated with atherosclerosis." (PMID 36032780, 2022). "Future studies should exploit spatiotemporally controlled CREB1 transgenic animal models to carefully delineate the role of CREB1 in atherosclerosis." (PMID 35186922, 2022). "Spatiotemporally controlled CREB1 transgenic animal models should be employed in future studies for delineating the implied role of CREB1 in atherosclerosis." (PMID 36186432, 2022). "These discrepant roles of CREB1 may allude to its coupling to various signaling pathways targeting either the stimulation or suppression of progression in atherosclerosis." (PMID 36186432, 2022). "CREB1 has been shown to be involved in both positive and negative regulation of atherosclerosis." (PMID 36186432, 2022).
bladder cancer (26 papers, 2011 to 2026). "Moreover, in bladder cancer cells, CREB1 has been implicated in epithelial to mesenchymal transition, a carcinogenic process which is non-significantly associated with the HPV status of squamous cell oropharyngeal carcinoma." (PMID 31766385, 2019). "From this overview, it can be seen that miR-433-3p targeting mRNA encoding the cAMP Response Element-Binding protein 1 (CREB1) has been found in cancer cells of various types including CRC, bladder cancer and HCC." (PMID 35922756, 2022). "UCA1/miRNA204-5p/cAMP responsive element binding protein-1 (CREB1) axis, UCA1/miRNA-143/Fos-like antigen 2 (FOSL2) axis, and UCA1/miRNA-196a-5p/CREB axis were involved in enhancing the chemoresistance of colorectal, ovarian, and bladder cancers." (PMID 34544452, 2021). "Creb1 is also a direct target of miR-122, which can promote cell proliferation and invasion in bladder cancer." (PMID 33494070, 2021). "Thus, recently discovered CREB1 offers a viable therapeutic target for the treatment of bladder cancer and may offer additional insight into the development of the bladder cancer." (PMID 36803831, 2023). "Conversely, increased expression of circRNA_0013936 has been reported to suppress bladder cancer cells by activating JAK2 and CREB1." (PMID 39628486, 2024). "Determination of the level of XPC gene 5' regulatory region DNA co-precipitated with the transcription factors CREB1 and Sp1 by IP in both untreated and VPA-treated HTB4 and HTB9 bladder cancer cells a." (PMID 21507255, 2011).
ovarian carcinoma (26 papers, 2013 to 2026). A malignant neoplasm originating from the surface ovarian epithelium. "Through quantitative lactyl-proteomics, we found CREB1 K122 as a hyperlactylated site specifically enriched in cisplatin-resistant ovarian cancer cells and patient tissues." (PMID 42212318, 2026). "Together, inhibition of the Ca2+ mediated CAMK2D/CREB1 pathway appears to be a promising therapeutic target for doxorubicin resensitization in ABCB1-mediated MDR ovarian cancer." (PMID 36439493, 2022). "This also suggests that CREB1 is an important protein that promotes ovarian survival and plays an important role in the development of ovarian cancer." (PMID 33921660, 2021). "Next, we analyzed the endogenous levels of CREB1 in ovarian cancer cell lines, and the results showed that the mRNA expression levels of CREB1 were higher in early-stage cells than in late-stage cells in different ovarian cancer cell lines." (PMID 33921660, 2021). "We identified human ovarian cancer tissue microarray and different stages of ovarian cancer cells for analysis of CREB1 protein and mRNA levels." (PMID 33921660, 2021). "In short, we found that the expression of the CREB1 gene in ovarian cancer tissue was significantly higher than that of normal ovarian tissue." (PMID 33921660, 2021). "In this study, we demonstrate that aberrant regulation of the Ca2+-mediated CAMKIID/CREB1 pathway contributes to ABCB1 over-expression and MDR creation and that CAMKIID and CREB1 are attractive targets for restoring doxorubicin efficacy in ABCB1-mediated MDR ovarian cancer." (PMID 36439493, 2022). "The high expression of the CREB1 gene may be an indicator of poor prognosis in ovarian cancer patients." (PMID 33921660, 2021). "The CREB1 gene may play a role in the occurrence and development of ovarian cancer by regulating the process of protein." (PMID 33921660, 2021). "Since naloxone has been approved for clinical treatment of lung cancer, our results may support the use of CREB1 gene status as an ovarian cancer biomarker and precision treatment of OV patients with naloxone." (PMID 33921660, 2021). "In ovarian cancer, transcription factors such as transcription factor 21 (TCF21), cAMP response element binding protein 1 (CREB1), and suppressor of mothers against decapentaplegic homolog (SMAD2/3/4) have emerged as critical regulators of this process." (PMID 41590379, 2026). "In fact, either the CAMK2 or CREB1 inhibitor resensitizes doxorubicin-resistant ovarian cancer cells, showing that the CAMK2/CREB1 pathway is a suitable target pathway for future therapeutic development." (PMID 36439493, 2022). "Our work unveils the lactate-CREB1 K122la-HMGB1-NETs axis as a metabolic-epigenetic-immune driver of cisplatin resistance and provides a promising nanomedicine strategy for overcoming treatment resistance in ovarian cancer." (PMID 42212318, 2026). "In addition, inhibiting the CAMK2/CREB1 pathway resensitized MDR ovarian cancer cells to not only doxorubicin but also paclitaxel and topotecan, which are clinically employed to treat ovarian cancer." (PMID 36439493, 2022). "In addition, significantly reduced expression of CREB1 protein was demonstrated in those cells, thus confirming the importance of lncRNA DQ786243 in relation to the amount of CREB1, but also the ability of both factors to modulate the proliferation of ovarian cancer cells." (PMID 36497095, 2022).
clear cell sarcoma (24 papers, 2010 to 2026). A rare malignant neoplasm with melanocytic differentiation characterized by the presence of polygonal or spindle shaped clear cells. "RT-PCR is recommended to confirm the gene fusion.8) However, the fusion of EWSR1 with CREB1 itself has also been reported in other tumors such as hemangioma-like fibrous histiocytomas and soft tissue clear cell sarcomas." (PMID 40242429, 2025). "Detection of EWSR1 gene rearrangement and/or confirmation of an EWSR1::ATF1 or EWSR1::CREB1 gene fusion confirms the diagnosis of clear cell sarcoma." (PMID 39264472, 2024). "For instance, EWSR1 or FUS can fuse to ATF1 or CREB1 in clear cell sarcoma of soft tissue as well as angiomatoid fibrous histiocytoma." (PMID 34081036, 2021). "Another translocation of EWSR to CREB1, a gene at 2q13, has also been described in a subset of clear cell sarcomas." (PMID 29072181, 2018). "We have recently demonstrated that the use of human embryonic stem mesenchymal progenitors (hES-MP) is important in the generation of Clear Cell Sarcoma (CCS) and Angiomatoid Fibrous Histiocytoma (AFH) models harboring the EWSR1::ATF1/CREB1 translocations." (PMID 36801905, 2023). "CREB family (CREB1, ATF1, and CREM) gene fusions are defining markers in diverse mesenchymal neoplasms (clear cell sarcoma, angiomatoid fibrous histiocytoma, and others)." (PMID 34228212, 2022).
osteosarcoma (23 papers, 2009 to 2025). A usually aggressive malignant bone-forming mesenchymal neoplasm, predominantly affecting adolescents and young adults. "LINC00665-drived polypeptide has tumor-suppressor features in osteosarcoma cells through repression of motility and proliferation by distracting the interaction of CREB1 and RPS6KA3." (PMID 38351332, 2024). "All significant peptides were higher phosphorylated in osteosarcoma cell lines, except for a peptide present in CREB1." (PMID 24447333, 2014). "Notably, a separate study has shown that downregulation of miR-1291 by osteosarcoma-derived exosomal ELFN1-AS1 promotes macrophage M2 polarization via upregulating CREB1." (PMID 39748408, 2025). "Specifically, lncRNA UCA1 positively modulates the PI3K/AKT/mTOR signaling pathway by sponging miR-582 and activating the target protein CAMP responsive element binding protein 1 (CREB1), inducing EMT in osteosarcoma cells." (PMID 37384249, 2023). "Notably, it has been demonstrated that UCA1 increases CREB1 expression by acting as a competitive endogenous RNA (ceRNA) of miR-582, thus promoting EMT via the CREB1-mediated mTOR pathway, which results in osteosarcoma metastasis." (PMID 33777227, 2021).
viral infection (22 papers, 2013 to 2025). "In conditions where caspases are inhibited, for instance in viral infection or chemical perturbation, both CREB1 and SRF induce expression of genes that are pro-survival." (PMID 27125827, 2016). "Concurrently, CREB1 inhibitors (666‐15) have been tested preclinically that inhibited CREB1 activity by disrupting its interaction with coactivators, showing efficacy in models of osteoarthritis and viral infections." (PMID 40794013, 2025).
dementia (21 papers, 2013 to 2024). Loss of intellectual abilities interfering with an individual's social and occupational functions. "Furthermore, transcription factors deregulated in the OB of mixed dementia subjects such as cAMP Responsive Element Binding Protein 1 (CREB1) and AP-1 Transcription Factor Subunit (c-Jun) were not differentially modulated at olfactory level across AD grading." (PMID 29050232, 2017).
sarcoma (21 papers, 2010 to 2026). A usually aggressive malignant neoplasm of the soft tissue or bone. "PPMS with EWSR1::CREB1 fusion is an exceedingly rare low-grade malignant sarcoma, typically found in the bronchi and lung parenchyma." (PMID 38421462, 2024). "A number of studies described gene rearrangements of the Ewing’s sarcoma (EWS) gene with CREB1 in various rare diseases, such as clear cell sarcoma (CCS), CCS associated with the gastrointestinal tract, and angiomatoid fibrous histiocytoma." (PMID 32347317, 2020). "CREB1 is the only other gene in this region previously identified in sarcoma translocations, and a break-apart CREB1 probe was created and applied to the cultured specimen." (PMID 20598147, 2010). "As with other sarcomas, each case of CCS is primarily driven by a single mutation particular to each tumour and for CCS genomic translocation results in the fusions of EWSR1 with ATF1 or, rarely, with CREB1." (PMID 33669307, 2021). "E-cadherin overexpression in sarcomas reduces anchorage-independent growth and spheroid formation of sarcoma cells through downregulation of phosphorylated CREB1 (p-CREB) and the transcription factor, TBX2, thus inhibiting sarcoma aggressiveness by preventing anchorage-independent growth." (PMID 33076339, 2020). "Interestingly, only one case exhibited the EWSR/CREB1 rearrangement, highlighting the predominance of the EWS/ATF-1 fusion in this specific sarcoma subtype." (PMID 38755643, 2024). "In this study, they included CIC::DUX4, BCOR-altered, EWSR1::ATF1/CREB1, and YWHAE::NUTM2B sarcomas, as well as fusion-negative SRCSs, reflecting the expanding molecular landscape within this spectrum." (PMID 41514642, 2025). "Interestingly, unlike most types of cancer, in which CREB1 commonly regulated genes are mainly upregulated, stomach adenocarcinoma (STAD) and sarcoma (SARC) upregulate and downregulate CREB1 commonly regulated genes on a comparable scale." (PMID 34641874, 2021).
mood disorder (19 papers, 2010 to 2025). A cognitive disorder a disturbance in which the person's mood is hypothesized to be the main underlying feature. "In fact, the major citing documents suggested that some genetic regions (e.g., CREB1 gene) show a significant correlation with mood disorders." (PMID 36833279, 2023). "It is therefore possible that an interaction of BDNF, CREB1, GNAS, and POMC genes with exposure to chronic stress or traumatic life events increase the risk of cardiometabolic and mood disorders either simultaneously, or through mediating factors." (PMID 28117839, 2017).
type 2 diabetes (19 papers, 2013 to 2025). "Of the predicted upstream regulators of the DEGs, CREB1, ERB2 and BMP2 were activated, as was the pathway that is modulated by the anti-Type 2 Diabetes pharmaceutical agent Troglitazone." (PMID 26987907, 2016).
bipolar disorder (17 papers, 2008 to 2025). A disorder of the brain that causes unusual shifts in mood, energy, activity levels and the ability to carry out day-to-day tasks. "CREB1 encodes a transcription factor involved in calmodulin-induced pathways and has been linked to bipolar disorder in 15 PubMed articles." (PMID 40427743, 2025). "Furthermore, proteomic data revealed unique disease-associated genes that were not identified using transcriptomic data, such as the association between bipolar disorder and CREB1." (PMID 40427743, 2025). "For bipolar disorder, CREB1 was exclusively identified by the protein-based fine-mapping method (p = 7.9 × 10−5)." (PMID 40427743, 2025). "For example, a gene called CREB1 was linked to bipolar disorder based on protein data but not RNA data." (PMID 40427743, 2025).
angiomatoid fibrous histiocytoma (16 papers, 2012 to 2025). "Similarly, low split signals for CREB1 and ATF1 lowered the possibility of angiomatoid fibrous histiocytoma." (PMID 34797454, 2021).